IL6 (interleukin 6)
Diseases named in the same sentence as IL6 in open-access papers (continued):
Sharing a sentence is not in itself a finding about the gene and the disease.
fibromyalgia (65 papers, 2015 to 2026). A chronic disorder of unknown etiology characterized by pain, stiffness, and tenderness in the muscles of neck, shoulders, back, hips, arms, and legs. "Fibromyalgia has also been associated with a low-grade pro-inflammatory profile with elevated levels of IL-6 and IL-8 being repeatedly found in the serum and plasma of fibromyalgia patients, associated with pain intensity, fatigue, and cognitive symptoms." (PMID 41225995, 2025). "The IL-6 molecule through activating the Jak/STAT3 pathway plays an essential role in fibromyalgia pathogenesis by causing excessive chemokines production and triggering the activation of glial cells." (PMID 39920875, 2025). "Studies have demonstrated an association between higher FIQ-R scores and increased IL-6 levels in patients with fibromyalgia." (PMID 39202077, 2024). "The relationship between FIQ-R scores and interleukin 6 (IL-6) levels offers additional insights into the mechanisms underlying fibromyalgia symptomatology." (PMID 39202077, 2024). "IL-8 and IL-6 are associated with platelet hyperactivity and peripheral activation in the nervous system of platelets in fibromyalgia due to the cytokines could lead to a lower MPV centrally." (PMID 35702479, 2022). "This study aims to investigate the effects of resistance training (RT) before hyperalgesia induction on pain sensitivity, IL-6 and IL-10 expression in skeletal muscle, and thalamic serotonin levels in a fibromyalgia (FM)-like rat model." (PMID 40566503, 2025). "IL-6 has also be found to be raised in patients with other chronic pain disorders including fibromyalgia." (PMID 40236898, 2025). "Inflammatory cytokines, such as IL-1 and IL-6, have also been reported to alter the balance of cortisol and adrenocorticotropic hormone, leading to fibromyalgia and chronic fatigue (Zadeh, Wilson & Agrawal, 2023)." (PMID 39056056, 2024). "While no linkage was established between vitamin K levels and FM, positive correlations were found between IL-6 and the Fibromyalgia Impact Questionnaire (FIQ), and between TNF-alpha and physical role difficulty." (PMID 38257075, 2024). "The interrelationship between fibromyalgia and inflammatory biomarkers, such as IL-6, IL-8, and TNF-α, has been the subject of an increasing number of studies." (PMID 39202077, 2024). "PBMC cultures from both groups exhibited a similar capacity to secrete IL-6 and IL-10 after stimulation, with a tendency for a lower stimulation index for IL-6 in the fibromyalgia group." (PMID 38399559, 2024). "This study aimed to investigate the relationship between serum levels of interleukin-6 (IL-6) and serotonin with the clinical parameters observed in patients with fibromyalgia." (PMID 39202077, 2024). "Increased levels of pro-inflammatory cytokines, such as TNF-α, IL-1β and IL-6 and their mediators, were detected in the suffering animals compared to the controls, confirming the key role of inflammation in fibromyalgia." (PMID 36979771, 2023). "In another pilot clinical trial, treatment with naltrexone resulted in marked inhibition of proinflammatory cytokines levels including IL-1β, IL-6 and TNF-α and reduction of fibromyalgia-associated nociplastic pain." (PMID 37069462, 2023). "A previous randomized controlled trial found that plasma levels of TNF-α and IL-6 were elevated in fibromyalgia patients." (PMID 37069462, 2023). "This study employed a well-established experimental animal model of fibromyalgia to investigate the role of IL-6 in this syndrome." (PMID 36979771, 2023). "In summary, our study showed that IL-6 has a key role in fibromyalgia, activating the Jak/STAT3 pathway, chemokine overexpression and glial-cell activation." (PMID 36979771, 2023). "We have already mentioned the nature of IL-6 and IL-8 in fibromyalgia syndrome (FMS); however, these cytokines have systemic knock-down effects." (PMID 35702479, 2022).
fibromyalgia (continued). "In some studies conducted on the plasma of patients with fibromyalgia, an increase in pro-inflammatory cytokines, such as IL-6, interleukin-8 (IL-8), IL-1β, and TNF-α, was found." (PMID 35566735, 2022). "A recent study showed that low intensity aerobic exercise associated with oral supplementation of tryptophan in rats with fibromyalgia diminished the pro inflammatory cytokine IL-6 release in muscles, as well as serum cortisol levels." (PMID 33848308, 2021). "With regards to fibromyalgia, a review of 25 selected studies revealed higher serum levels of IL-6 vs. controls." (PMID 35295453, 2021). "Patients with fibromyalgia were reported to show higher serum levels of IL-1 receptor antagonist, IL-6, and IL-8." (PMID 32198578, 2020). "A systematic review and meta-analysis of 13 studies reporting inflammatory biomarkers in fibromyalgia found only plasma interleukin-6 (IL-6) to be higher in patients, compared to controls." (PMID 32192466, 2020). "Elevation of IL-1β, IL-6 and IL-8, and mast cells mediating microglia activation through the production of proinflammatory cytokines were found in patients with fibromyalgia." (PMID 33002009, 2020). "Several studies have indicated that the levels of proinflammatory cytokines such as IL-1, IL-6, and IL-8 are elevated in the blood of patients with fibromyalgia." (PMID 32774811, 2020). "This suggests that by controlling the IL-6 route, it may be possible to reduce pain-related symptoms in individuals suffering from fibromyalgia." (PMID 39920875, 2025). "The cytokines IL-6 and IL-10 were selected because they represent key pro- and anti-inflammatory mediators involved in the nociceptive sensitization and immune dysregulation observed in fibromyalgia." (PMID 40566503, 2025). "IL‐6, CSF‐1 have been highlighted in a previous proteomics study on fibromyalgia." (PMID 41170664, 2025). "In fibromyalgia (FM), serum levels of pro-inflammatory cytokines such as interleukin-6 (IL-6), interleukin-8 (IL-8), interleukin-1 beta (IL-1β), and tumor necrosis factor-alpha (TNF-α) are frequently elevated, whereas concentrations of anti-inflammatory cytokines are typically reduced." (PMID 41002443, 2025). "Thus, to evaluate the expression profile of IL-6 in fibromyalgia, further molecular analyses were performed." (PMID 36979771, 2023). "Our data suggest that the modulation of the IL-6 pathway could attenuate pain-like behavior in fibromyalgia-dependent pain." (PMID 36979771, 2023). "Also, a correlation between MMP-3 and IL-6 was proposed in fibromyalgia, a common chronic pain, which represents either inflammatory cytokine-induced MMP-3 release or MMP-3 stimulation of local inflammatory cytokine production." (PMID 36684250, 2022). "For instance, T helper 2 (Th2) anti-inflammatory cytokines, including IL-4, IL-5 and IL-13, have been reported to decrease in fibromyalgia patients, whereas inflammatory cytokines IL-6 and IL-8 are found to elevate in fibromyalgia, indicating a potential role in the chronic pain of fibromyalgia." (PMID 33912165, 2021). "Chronic systemic inflammation might lead to neuroinflammation and is considered to play a role in the pathogenesis in fibromyalgia, with antibodies such Interleukin-1Ra or Interleukin-6 elevated in patients' serum." (PMID 33777972, 2021). "Interestingly, an increase in cytokine concentrations (i.e., IL-1RA, IL-6, and IL-8) has been observed in patients with fibromyalgia." (PMID 33909692, 2021). "Patients with fibromyalgia have high serum levels of IL-1RA and IL-6." (PMID 28226002, 2017). "Therefore, we speculate that miRNA-217 might be an upstream miRNA in fibromyalgia that controls IL-6." (PMID 39920875, 2025). "Although the causal relationship between IL-6 and fibromyalgia has not been fully elucidated, there is evidence that systemic inflammation and immune system activation may play a role in the pathogenesis and clinical manifestations of the disease." (PMID 39202077, 2024).
fibromyalgia (continued). "In general, the strength of this association was greater than that seen for IL-6 levels with the SS score (with the exception of the UCTD sub-group) and also was greater for individuals without a fibromyalgia diagnosis as compared to those with a fibromyalgia diagnosis." (PMID 31685018, 2019). "Compared with controls, patients with fibromyalgia, a condition marked by widespread pain and fatigue, presented significantly elevated levels of CRP and IL-6, which correlated positively with measures of pain sensitivity and emotional distress." (PMID 41373439, 2025). "Indeed, there is evidence that high serum concentrations of cortisol associated with stress might worsen ache in individuals with fibromyalgia and potentialize the pro-nociceptive influence of inflammatory markers like IL-6 and tumor necrosis factor-alpha (TNF-α)." (PMID 39404410, 2024). "A recent systematic review and meta-analysis of 29 studies (N=2458) reported significant increases of TNF, IL-6, IL-8 and IL-10 in CWP/fibromyalgia patients compared with healthy controls." (PMID 39231552, 2024). "Systematic review and metanalyses have shown that pro-inflammatory cytokines, interleukin-6 (IL6) and interleukin-8 (IL8), are found to be elevated in fibromyalgia." (PMID 35702479, 2022). "Elevated levels of IL-6, IL-17A and a dysregulated HPA have also been observed in fibromyalgia patients demonstrating additional overlap between chronic pain states and idiopathic organ/endocrine dysfunction." (PMID 35295453, 2021). "The objective of this study was to verify the effects of aerobic exercise associated with tryptophan (TRP) supplementation on hyperalgesia, as well as on cortisol, IL-6 and TNF concentrations in female rats with experimental fibromyalgia (FM)." (PMID 30785911, 2019). "Further, the release of IL-1β, IL-6, and TNF during moderate exercise has also been shown to be higher in patients with fibromyalgia than healthy controls." (PMID 26624891, 2015). "In the fibromyalgia model induced by intermittent cold stress (ICS), electroacupuncture treatment and TRPV1 deletion reversed the increase in IL-6 in female mice plasma and reduced heat and mechanical hyperalgesia, indicating the role of IL-6 in electroacupuncture-treated fibromyalgia." (PMID 40332543, 2025). "This may be related to overlapping inflammatory profiles, including elevated levels of IL-1β, IL-6, TNF-α, and IL-17, which are characteristic of FMF, CD, and fibromyalgia." (PMID 41451232, 2025). "The finding of elevated levels of these neuropeptides alongside IL-6 and TNF in fibromyalgia patients raises the possibility of mast cell origin of the inflammatory cytokine signature of fibromyalgia and supports a bidirectional interaction between pain-mediating substance P and mast cells." (PMID 40002538, 2025). "In particular, studies have demonstrated elevated expression of pro-inflammatory cytokines such as IL-6, IL-8, and TNF-α in monocytes from fibromyalgia patients, suggesting monocyte activation may contribute to systemic and central sensitization processes." (PMID 41517404, 2025). "Salivary IL-6 (and cortisol) increased after pain pressure in patients with fibromyalgia but not in healthy subjects." (PMID 38385158, 2024). "Similarly, infliximab administration to rats with reserpine-induced fibromyalgia inhibited microglial stimulation via decreasing the expression of P2X7R and its downstream p38-MAPK, resulting in low levels of IL-1β, IL-6 and TNF-α." (PMID 37069462, 2023). "Finally, one review found that the difference in levels of IL-6, IL-8, TNF-α, and brain-derived neurotrophic factor (BDNF) may have the potential to be used for stratification of patients with fibromyalgia into subgroups for future targeted therapies." (PMID 41598488, 2026).
fibromyalgia (continued). "Recent studies identify an imbalance in cytokine levels in fibromyalgia patients, characterized by elevated tumor necrosis factor-alpha (TNF-α), interleukin-6 (IL-6), and interleukin-8 (IL-8), with serum concentrations of IL-6 and IL-8 significantly correlating with disease severity." (PMID 40407467, 2025). "It is conceivable that mediators of inflammation, like interleukin 1β, IL-6 and TNF-α, that are elevated in the brain of animals with acid saline-induced fibromyalgia may activate IDO, which, in the presence of an excess of Trp, would lead to increased KYN levels in the brain." (PMID 39404410, 2024). "Although plasma cytokines were not analyzed in this study, muscle levels of IL-6 and IL-8 (but not IL-1β or TNF) were reported higher than plasma levels in patients with fibromyalgia, supporting that they are produced in the muscle." (PMID 28243900, 2017). "Thus, this study indicates that IL-1β, IL-6, IL-8, and TNF do not seem to play an important role in maintenance of muscle pain in fibromyalgia." (PMID 26624891, 2015).
mood disorder (65 papers, 2013 to 2025). A cognitive disorder a disturbance in which the person's mood is hypothesized to be the main underlying feature. "Proinflammatory cytokines, particularly interleukin 6 (IL-6), have been implicated in the pathogenesis of both pSS and mood disorders." (PMID 40822847, 2025). "Pro-inflammatory cytokines such as TNF-α, IL-1β, IL-6, and IL-17, which play central roles in the pathogenesis of RA, are also implicated in the development of mood disorders." (PMID 40943274, 2025). "Four biological parameters were selected that in earlier research were found to be associated with inflammatory events in mood disorders: IL-6, CRP, Zn, and albumin levels." (PMID 38785543, 2024). "Studies indicate that carotenoids can inhibit nuclear factor-kappa B (NF-κB) and downregulate pro-inflammatory cytokines such as interleukin-6 and tumor necrosis factor-α, reducing neuroinflammation associated with mood disorders." (PMID 39749353, 2024). "It has been proposed that IL-1β, IL-6, and TNFα can directly modulate neuronal plasticity and cause mood disorders." (PMID 33402212, 2021). "The most prominent cytokines associated with mood disorders include: interleukin-1 beta (IL-1ß), interleukin-6 (IL-6), tumor necrosis factor alpha (TNF-alpha), and C-reactive protein (CRP)." (PMID 34113269, 2021). "IL-6 is implicated in mood disorders and is a reliable marker of inflammation in the brain." (PMID 40487411, 2025). "Neuroinflammation has been increasingly implicated in mood disorders, with elevated pro-inflammatory cytokines such as interleukin-6 (IL-6), tumor necrosis factor-alpha (TNF-α), and C-reactive protein (CRP) contributing to neuronal dysfunction and treatment resistance." (PMID 40969698, 2025). "Furthermore, proinflammatory cytokine expression and circulating levels, like interferon gamma (INFγ), TNFα, IL-6, and IL-1β, are associated with mood disorder symptoms." (PMID 32377159, 2020). "In addition, increased inflammation markers and pro-inflammatory cytokines, such as tumor necrosis factor-alpha and interleukin-6, in patients with mood disorders may offer another plausible explanation for the association of these mood disorders with NAFLD." (PMID 33537324, 2020). "LPS administration is known to elevate cytokine levels such as IL-1β, IL-6, and TNF-α, which contribute to neuroinflammation and are implicated in mood disorders." (PMID 40487411, 2025). "Interleukin-6 (IL-6) and IL-8, measured 2–14 weeks post-ACS, were associated with mood disorders at baseline and 1 year follow-up." (PMID 40912718, 2025). "Bioinformatic analyses revealed enrichment in pathways related to neurodegeneration and mood disorders, identifying key targets such as IL‐6, MAPK, and NOS2." (PMID 40212473, 2025). "Significantly increased levels of TGF-β, IL-10, and IL-6 in SD compared to MD or ND subjects can suggest the role of cytokines in mood disorders in SD group." (PMID 38646609, 2024). "Stress-induced increases in LPS are paralleled by higher levels of proinflammatory cytokines, such as interleukin-6 (IL-6) and tumor necrosis factor-alpha (TNF-α), which have also been implicated in mood disorders." (PMID 38476949, 2024). "The correlation between IL-6 and the MOOD-SR scores is in line with the growing evidence of alterations in IL-6 levels in patients with mood disorders, especially MDD." (PMID 37371695, 2023). "This process, also called “cytokine induced mood-disorder” can be induced by the systemic release of inflammatory cytokines including tumor necrosis factor alpha (TNFα), interleukin-6 (IL-6) and interleukin-1 beta (IL-1β)." (PMID 31734534, 2019). "Moreover, the activation of CREB by CRTC1 has been linked to improvements in mood disorders, with evidence that CREB can bind to the promoter region of the IL-6 gene, thus influencing IL-6 transcription." (PMID 40843259, 2025).